CD4 (CD4 molecule)
Diseases named in the same sentence as CD4 in open-access papers (continued):
Sharing a sentence is not in itself a finding about the gene and the disease.
Opportunistic infection (continued). "The clinical characteristics of the participants were assessed, including clinical staging level, viral load and CD4 level, as well as the comorbidity of the common opportunistic infections." (PMID 32742296, 2020). "The advanced age of the child, the higher baseline level of hemoglobin, the baseline WHO clinical stage II, and opportunistic infections contributed to changes in CD4 counts." (PMID 32476985, 2020). "Individuals with low CD4 count tend to have reduced immunity, higher incidence of opportunistic infection and hospital admission." (PMID 32818041, 2020). "Late presenters for HIV care were still commonly encountered, with 34.6% presenting with a CD4 lymphocyte count <200 cells/μl, 61.5% <350 cells/μl, and 16.5% having at least one opportunistic infection." (PMID 32530918, 2020). "Despite this, advanced HIV disease (CD4 less than 200 cells/mL) and opportunistic infections remain a persistent challenge and contribute significantly to HIV-associated mortality, which equates to 23,000 deaths in Uganda in 2018 alone." (PMID 33274313, 2020). "In the era of universal test and treat, the evaluation of CD4 count is still crucial for guiding the initiation and discontinuation of opportunistic infections prophylaxis and assessment of late presenting patients." (PMID 32228483, 2020). "HIV induced systemic loss of CD4 T cells increases susceptibility to different opportunistic infections, including HPV.Similarly, depletion of CD4 T cells at mucosal sites and within the genital tract during HIV infection has previously been demonstrated." (PMID 33007050, 2020). "A CD4+ threshold ≥ 200 cells/μL is also recommended to minimise the likelihood of occult opportunistic infections either manifesting after organ recovery or being transmitted to the donor during transplantation." (PMID 33240537, 2020). "Clinical variables such as CD4 cell count, HIV stage, adherence to medication, adverse drug reaction, history of other chronic illness and opportunistic infection showed significant association." (PMID 31429805, 2019). "Even though normal rates of CD4+ T cells and freedom from opportunistic infections are achieved, these immune changes potentially affect the outcome of endemic/epidemic infections that HIV-infected subjects are also exposed to." (PMID 31068600, 2019). "As there is no consensus on the definition of successful immunological recovery, we were interested in the minimal CD4 count before opportunistic infections typically become evident in poor immune responders." (PMID 30802257, 2019). "On the other hand, HD patients are more prone to such opportunistic infections, where repeated HD decreases CD4+ counts compared to predialysis and healthy controls." (PMID 31142275, 2019). "For instance, enumeration of CD4 T-cell lymphocytes with flow cytometry and IVD reagents has been widely used in HIV-infected patients, continues to be used to assess the risk of opportunistic infections." (PMID 30689658, 2019). "Guidelines recommend antimicrobial prophylaxis against such opportunistic infections based on the number of remaining CD4 positive T-lymphocytes (CD4+ T-cells) in circulation." (PMID 31510960, 2019). "The large proportion (around 50%) of lower CD4 counts (≤350 cells/mm3) also suggested a room for improvement in immune recovery, because the decline of CD4 count can lead to an increase of both opportunistic infections and mortality." (PMID 30822343, 2019). "The role of CD4 enumeration is still important where there is limited availability of ART for staging of drug treatment and monitoring, and for monitoring opportunistic infections in the HIV infected subjects at risk (CD4 <200 cells/μL)." (PMID 30689658, 2019). "With worseningWHO clinical staging and decreasing CD4 cell count, immune system is compromisedresulting in higher chances of becoming infected with opportunistic infections." (PMID 31013320, 2019).
Opportunistic infection (continued). "The majority, 376(91%) had CD4 count ≥200 cell/mm3, and about 154(37.3%) had history of opportunistic infections." (PMID 31689299, 2019). "The HIV sero-positive patient requires evaluation for opportunistic infections, and immune functions (CD4 and viral load)." (PMID 31552124, 2019). "Despite increased antiretroviral therapy (ART) coverage and the raised CD4 threshold for starting ART, opportunistic infections (OIs) are still one of the leading causes of death in sub-Saharan Africa." (PMID 30383836, 2018). "HAART reduces the decline in CD4 counts during chemotherapy, ameliorating the potential for opportunistic infections." (PMID 30409111, 2018). "Higher average CD4+ counts were observed in patients on ART compared to their ART-naïve counterparts; making the naïve patients to be at increased risk of having opportunistic infections." (PMID 29795558, 2018). "Several co-factors (such as viral load, CD4 cell counts, opportunistic infections, malignancies and others) have been proposed, at a certain extent, as co-factors in the phenomenon." (PMID 29576814, 2018). "Most of them (83.2%) had CD4 count less than 350 cell/mm3 at baseline and 226 (84.3%) had opportunistic infections (OIs) prior to HIV diagnosis." (PMID 29483948, 2018). "HIV infection is common and an estimated 120,000 have CD4 counts <200 × 106/mL and commonly present with opportunistic infection." (PMID 29601494, 2018). "ART is administered in order to mitigate HIV replication, which would subsequently lead to a rise in CD4+ count levels while providing protection against opportunistic infections." (PMID 29795558, 2018). "The need remains for expanded access to routine VL testing to verify patients’ adherence and treatment efficacy, and for CD4 as an indicator of immunocompromise to better target opportunistic infection testing." (PMID 29514239, 2018). "Lower levels of PA were associated with older age (2/2 studies), a lower number of CD4 cells/μl (1/1), a more severe HIV-stage (1/1), a higher HIV load (1/1), the presence of opportunistic infections (1/1) and a higher BMI (1/1)." (PMID 30602967, 2018). "A low CD4 cell count was demonstrated a strong predictor of thrombotic events as well as the stage of the disease and the presence of opportunistic infections and malignancies." (PMID 29576814, 2018). "An immunologic reserve (CD4 count) of less than 200 cells per cubic millimetre (mm3) is a threshold below which fatal opportunistic infections become common." (PMID 30133504, 2018). "Presence of opportunistic infection (p = 0.001), use of CPT (p = 0.04) and CD4 count < 200 cells/μl (p = 0.002) were associated with an increased risk of anemia." (PMID 29632668, 2018). "Further, the probability of increasing CD4 counts throughout the sampling interval is variable due to adherence, opportunistic infections, and drug resistance." (PMID 28199360, 2017). "Third, a 3-hour, in-factory training program for 50 workers was included and covered basic facts about HIV, CD4 counts, opportunistic infections and ARV to understand how HIV is treated and how to live and work with HIV-infected persons." (PMID 29037108, 2017). "High HIV VL was more likely to be found in patients with other markers of advanced HIV disease such as low CD4, low body weight, and current opportunistic infections." (PMID 28267790, 2017). "A literature review of 259 reported idiopathic CD4+ lymphopenia cases found that at diagnosis the mean age was 40.7 years, 62% of cases were male, 87.6% had one or more opportunistic infection, 14.2% had an autoimmune disease, and 18.1% had a malignancy." (PMID 28770187, 2017). "Prolonged CD4 T‐cell count after HSCT leaves patients at risk of mortality and morbidity due to opportunistic infection, so understanding factors associated with reconstitution is vital." (PMID 28074473, 2017).
Opportunistic infection (continued). "In the most immunosuppressed patients whose median CD4+ count was <200 cells/μL, HIV-associated vasculitis, opportunistic infections, and antiphospholipid syndrome were the most frequently found etiologies." (PMID 28931222, 2017). "The BD FACSPresto system provides results for both CD4 and %CD4 that are frequently used for monitoring co-infections, opportunistic infections, or treatment failure, and for HIV-infected populations that have no access to viral load testing." (PMID 29290885, 2017). "Clinically, a central concern is the potentially deleterious effect of CD4 T cell aplasia with regards to opportunistic infections, viral reactivation, and post-transplant lymphoproliferative disorder." (PMID 29348865, 2017). "In contrast, others have reported lower CD4+ cell counts in patients with myeloma who develop opportunistic infection following intensive combination conventional therapy." (PMID 29051761, 2017). "A CD4+ count below 200 cells/μL implies severe immunosuppression and precludes the discontinuation of primary prophylaxis against opportunistic infections (e.g., Pneumocystis pneumonia or Toxoplasma gondii encephalitis)." (PMID 29093707, 2017). "The only relevant misclassification level, if the WHO guideline to screen for cryptococcal disease or other opportunistic infection is applied, is thus at the CD4 ≤100cells/μl level." (PMID 29099874, 2017). "Meta-regression analysis revealed that a CD4 cell count <50 cells/μl upon cART initiation was an independent risk factor for IRIS, independently of the type of opportunistic infection." (PMID 28588577, 2017). "In the HIV-positive patient, CM is a late opportunistic infection, usually observed when the T lymphocyte CD4+ cell count falls below 50–100/μL, leading to an acute mortality in the developing world of about 13% to 55%." (PMID 28617817, 2017). "We compared the HIV history parameters for shedders and controls: the CD4 cell counts, mode of transmission, STI history, opportunistic infections and co-infections with HBV and HCV (usually associated with intravenous drug use)." (PMID 28904798, 2017). "The data on demography, date of HIV diagnosis, WHO stage, opportunistic infections, CD4, hemoglobin, ART regimen, and time and outcome on treatment as dead or alive were collected and analyzed using STATA version." (PMID 28702270, 2017). "Lower CD4 cell count and high PVL not only increases the risk of opportunistic infections but also enhances the transmission risk to sexual partners." (PMID 28763465, 2017). "The use of potent HAART is intended to induce sustained suppression of HIV viral replication allowing CD4 regain and restore the body’s ability to fight against opportunistic infections." (PMID 28595630, 2017). "Determination of CD4 count continues to be critical in decisions for screening and prophylaxis for major opportunistic infections, and when to stop." (PMID 29290885, 2017). "The relationship between the use of other drugs for the treatment of opportunistic infections and the adherence rate in the intervention group and the correlation between adherence and viral load and CD4 lymphocytes were also assessed." (PMID 29071230, 2017). "Generally, it is believed that reconstitution of the patient’s immune system, characterized by increased in CD4+ T cells and decline in viral load, results in the decline of opportunistic infections such as OPC." (PMID 28326084, 2017). "This allows CD4 gain to levels that are adequate enough to restore the body’s capability to fight against opportunistic infections (OIs)." (PMID 28595630, 2017). "These two elements, CD4 count and clinical stage, enabled the setting of thresholds for some therapeutic decisions such as the initiation of prophylaxis for the major opportunistic infections." (PMID 27462361, 2016).
Opportunistic infection (continued). "Data on socio-demographic characteristics, CD4 counts, viral loads (VLs), opportunistic infections, adverse effects of treatment, hospital admissions, and patient retention at 6, 12, 24, and 36 months on ART were collected." (PMID 29568601, 2016). "Previous studies have also found a relationship between low CD4 count and presence of opportunistic infection." (PMID 27253974, 2016). "Imperfect measures of retention such as repeat CD4 cell counts and attendance at clinic appointments can misclassify healthy persons arriving solely to receive refills for opportunistic infection prophylaxis." (PMID 26901765, 2016). "We preferred nadir than recent CD4 cell count because opportunistic infections and concomitant acute infections can lower the CD4 cell count." (PMID 27286652, 2016). "Maharaj reported that none of the participants showed any adverse effects on their clinical status of CD4 counts, viral load, or increase in opportunistic infections, heart, respiratory and blood pressure either during or after the exercise intervention." (PMID 27112335, 2016). "Further, in order to reduce opportunistic infections and probable deaths during treatment, cotrimoxazole prophylaxis should be maintained so as to raise the CD4 levels." (PMID 27642482, 2016). "Twenty-nine HIV1-infected patients (average 12 years of infection, nadir of CD4 210/mm3, including 7 patients with a history of opportunistic infection) with a biopsy-proven or likely HIVOP have been followed up for an average of 6.1 years." (PMID 26986141, 2016). "The mortality of patients with severe drug eruption, drug hypersensitive history, CD4+ T cell count ≤200 cells/μL, opportunistic infection, viral load ≥1 × 102 copies/mL, low ALB level or decreased RBC and Hb was significantly increased." (PMID 27796328, 2016). "This seems unlikely: only 7 of our 26 patients had a history of opportunistic infection, nadir CD4 cell count was quite high (210 cells/μl) in our patients, and all had controlled HIV disease." (PMID 26986141, 2016). "CD4 testing is, however, recommended for monitoring opportunistic infections of unstable or sick patients." (PMID 27175484, 2016). "The participants in this study presented low T CD4+ cell counts and a high viral load,supporting the literature and indicating that TB is an opportunistic infection, stronglyassociated with the decrease of the immunological system." (PMID 27192416, 2016). "The risk of opportunistic infections, at least those infections common in Western countries, is very low once ART is successful, even with low CD4 cell counts." (PMID 27431995, 2016). "The risk of developing liver enzyme abnormality was high among those with HBV and/or HCV infections, those with opportunistic infections, male patients, and those with low CD4 count." (PMID 27493798, 2016). "The following variables were included in the multivariate model: sex, age, study visit, WHO stage, education level, income per month, depression, employment status, alcohol use, social support, opportunistic infection and baseline CD4 count." (PMID 26216221, 2015). "There were statistically significant differences between the ART and basic care groups for sex, alcohol consumption, WHO stage, opportunistic infection, and median CD4 cell count." (PMID 26039733, 2015). "HIV impairs the host’s immune system, setting the stage for the emergence of opportunistic infections like TB, as in our study subjects, and further depletion of CD4 cells ultimately leading to illness requiring medical intervention." (PMID 25941570, 2015). "Disease progression of smoldering ATL along opportunistic infections was observed with very high levels of serum sIL-2R (14,058 U/mL) and an increased percentage of CD4+CD25+ T cells (87.2%) in peripheral blood." (PMID 26693362, 2015). "Both patients showed significant increases in the CD4+CD25+ T cell subpopulation in peripheral blood in addition to opportunistic infections." (PMID 26693362, 2015).
Opportunistic infection (continued). "While ART and CD4 cell counts are provided free of charge within the national program, treatment and care for opportunistic infections has to be covered by the patient." (PMID 26606057, 2015). "These included provision of CPT at enrolment, service availability, CD4 cell count, opportunistic infections, WHO clinical stage, and HIV status disclosure." (PMID 26034602, 2015). "A study by Schacker and colleagues found that patients with relatively high numbers of naive CD4+ T-cells were less likely to have failure of immune reconstitution with ART and had lower risk of opportunistic infections and mortality." (PMID 26083409, 2015). "Progressive reduction in CD4 cell population reduces the ability of the body to ward off infective agents leading to occurrence of opportunistic infections in HIV infected individuals." (PMID 26136407, 2015). "In one study of HIV positive individuals, several parasitic infections occurred more frequently in those with low CD4 cell counts, as is the case with opportunistic infections." (PMID 25768005, 2015). "In our observation, monitoring the CD4+CD25+ T cell subset over time in the occurrence of opportunistic infections seems to be a useful prognostic biomarker in HTLV-1 carriers and in smoldering ATL." (PMID 26693362, 2015). "For example, a low CD4 count in HIV patients makes them prone for opportunistic infections such as Pneumocystis jirovecii pneumonia (formerly Pneumocystis carinii)." (PMID 26468883, 2015). "Similar to our reported case, patients with Idiopathic CD4+ Lymphocytopenia (ICL) go undiagnosed until they develop symptoms suggestive of opportunistic infections." (PMID 26448886, 2015). "The routine current practice at ART clinics used CD4 counts as a reminder for occurrence of opportunistic infections." (PMID 26000175, 2015). "The majority of patients were male (152/236 patients, 64.4%) with a low median CD4 count (52 cells/mm3); 12.2% also had other opportunistic infections at TB diagnosis." (PMID 25623609, 2015). "Higher CD4 cell counts at initiation resulted in lower laboratory and opportunistic infection treatment costs." (PMID 26424195, 2015). "The model simulated treatment over a lifetime horizon by tracking change in patients’ CD4 count, occurrence of clinical events (opportunistic infections, cancer and cardiovascular events), treatment switch and death." (PMID 25394109, 2014). "It is likely that individuals in later stages of disease progression, as measured by CD4+ count, viral load, or opportunistic infections, also experience a higher burden of HIV symptoms." (PMID 25551656, 2014). "Even allowing those opportunistic infections will still occur in those with higher CD4 counts; those infections should be milder and therefore require shorter average hospitalizations." (PMID 24977038, 2014). "Other reports also showed that most opportunistic infections co-existing acute HIV infection occurred when CD4+ T cell counts temporarily dropped." (PMID 25160905, 2014). "The higher CD4+ groups reflected earlier landmarks used to guide treatment initiation while the lower CD4+ groups related to risks of opportunistic infections and death." (PMID 25541953, 2014). "Seventeen patients had less than 15% of naive CD4+ T cells, a condition recently named late onset combined immune deficiency (LOCID) described in a subgroup of CVID patients at high risk of opportunistic infections." (PMID 24741616, 2014). "Medical chart abstraction was performed approximately one year after initial screening to obtain data on clinic visit history, ART use, CD4 count, opportunistic infections, and patient outcome." (PMID 24465651, 2014). "In untreated individuals, the number of CD4+ T-cells in the blood slowly drops over time and the patient eventually succumbs to an opportunistic infection." (PMID 24651404, 2014).